CRP (C-reactive protein)
Diseases named in the same sentence as CRP in open-access papers (continued):
Sharing a sentence is not in itself a finding about the gene and the disease.
viral infections (continued). "Eight (29%) believed it was a good discriminator between viral and non-viral infections in all scenarios in which CRP featured in their rank lists, while two (7%) believed it to be a good marker of disease severity." (PMID 36367878, 2022). "These gene transcripts distinguished bacterial from viral infections with a 97.3% sensitivity and 100% specificity with superior performance to CRP and leukocyte count." (PMID 35186993, 2022). "As expected, patients with a bacterial infection had higher CRP levels upon ED admission compared to patients with a viral infection (median CRP: 133 and 23.31, respectively, P < 0.001)." (PMID 36477474, 2022). "We compared the ability of ddhC to differentiate viral infection from other groups to alternative biomarkers, such as white cell count, lymphocyte count, and C-reactive protein (CRP), which were taken as part of routine admission clinical laboratory tests." (PMID 35128501, 2022). "Here we compared adaptive NK cell phenotypes in CMV DNA+ and CMV DNA− patients and considered inflammatory biomarkers invoked by viral infections [C-reactive protein (CRP) and soluble interferon receptor (sIFNR)-α/β]." (PMID 35292053, 2022). "An inflammatory pattern was observed, in line with active viral infection (CRP: 58.2 [22.9–136.7] mg/L, LDH: 659 [500–852.25] mg/dL, ferritin 1098.5 [634–1983.25] mg/dL, D-dimer 1030 [429–1703] mg/dL, and LYM 0.94 [0.57–1.14] cells/mm3)." (PMID 35453570, 2022). "The authors were able to create a cutoff of CRP velocity of 3.47 mg/dL/h as 93.8% specific and 50.2% sensitive for the diagnosis of a bacterial over viral infection." (PMID 35897672, 2022). "Several inflammatory markers, including leukocyte populations and validated CRP levels, should enable physicians to reliably identify children who need antibiotic treatment and help avoid treating those with viral disease." (PMID 36422508, 2022). "There was a significant difference between the eCRPv findings of patients with a bacterial infection and those with a viral infection for those with CRP findings in the range of 100–150 mg/L." (PMID 36477474, 2022). "CRP levels in a healthy person should remain below 5 mg/L, but are elevated when a person is fighting a bacterial or viral infection." (PMID 35893326, 2022). "We found higher CRP levels in male patients with clinically suspected myocarditis, a history of acute viral infection in the 6 months preceding diagnosis, shorter symptoms’ duration, and higher chest pain frequency and troponin I levels." (PMID 36498643, 2022). "Abnormal CRP was reported in 288 patients, mainly with CS myocarditis (p < 0.001), recent viral infection, shorter symptoms duration (p = 0.001), chest pain (p < 0.001), better functional class at diagnosis (p = 0.018) and higher troponin I values (p < 0.001)." (PMID 36498643, 2022). "While the axes IL-1β/IL-6 link to CRP production in bacterial infections, IL-18 production links to transferrin in viral infection." (PMID 35663992, 2022). "We have consistently found that plasma hepcidin levels have a superior predictive value in distinguishing bacterial from viral infections, particularly in bacterial enteritis and urinary tract infections in FC, and are correlated to CRP levels." (PMID 35740850, 2022). "Other potential approaches in the future include the introduction of ready access rapid diagnostic tests (point-of-care C-Reactive Protein Testing–POC-CRPT) in GP surgeries to help distinguish between bacterial and viral infections." (PMID 36290081, 2022). "Patients with bacterial infections had higher levels of CRP, leukocytes, neutrophils, eosinophils, and monocytes compared with patients with viral infections." (PMID 36095013, 2022). "Differences to the acute phase protein CRP include an earlier and sharper rise in the acute phase response, which occurs not only in bacterial but also in viral infections." (PMID 35345614, 2022).
viral infections (continued). "Patients with serum CRP of less than 12 mg/L were mainly assumed to have a viral infection, which is plausible since 61.52% of those with febrile neutropenia were positive with one of our viral tests." (PMID 35997401, 2022). "Having said that, other studies have reported that CRP testing is also widespread for self-limiting viral infections in countries where POCT is available." (PMID 36127630, 2022). "The performance of the validated models to diagnose bacterial vs. viral infections, as adjudicated by an expert panel, was compared to that of CRP and PCT single markers." (PMID 36362791, 2022). "More specifically, the classifier using the best eCRF variable CRP alone (“CC”), generated an average AUC of 0.75 in the 10 times repetitions and accuracies of 68% for bacterial infection and 70% for viral infection cases." (PMID 35436301, 2022). "In summary, C-reactive protein is a commonly used biomarker for detecting and differentiating between bacterial and viral infections." (PMID 35897672, 2022). "High levels of CRP as well as increased levels of cytokines including IL-6 can be detected which are very unusual to find elevated during a viral infection." (PMID 34079538, 2021). "It is important to note that CRP levels were significantly increased in bacterial infections than in viral infections." (PMID 33968148, 2021). "The CRP is an acute inflammatory protein and plays important roles in host responses against viral infection, which was upregulated during SARS-CoV-2 infection." (PMID 33859163, 2021). "The signature achieved higher net benefit in decision curve analysis than either CRP or leukocyte count for discriminating viral infections from all other infections." (PMID 34423323, 2021). "Given it is a viral disease, plasma levels of C-reactive protein (CRP), a common bacterial infection marker, are surprisingly high." (PMID 34408751, 2021). "TNF-related apoptosis induced ligand (TRAIL), interferon gamma induced protein-10 (IP-10), and C-reactive protein (CRP) exhibit differential expression in the blood in response to bacterial vs. viral infection." (PMID 34966702, 2021). "The AUROC of 0·974 in discriminating bacterial from viral infection exceeded the performance of either CRP or leukocyte count, which had AUROCs of 0·745 (95% CI 0·622−0·856) and 0·763 (0·647−0·863), respectively (appendix pp 16−17, 30)." (PMID 34423323, 2021). "A CRP cut-off value of 11 mg/L would miss a small proportion of bacterial infections, while also leaving an unsatisfactorily high proportion of viral infections wrongly classified and hence probably mismanaged with antibiotics." (PMID 34574070, 2021). "CRP is an acute phase protein released in hepatocytes after stimulation of IL-6 and IL-8 in response to acute inflammation, including viral infections, localized bacterial, and other inflammatory processes, and is involved in different immune functions." (PMID 33713309, 2021). "Apart from the high and persistent fever, the clinical symptoms in KD mimic both bacterial and viral disease presenting with lymphadenopathy, skin rash, red eyes, red tongue and/or red hands and feet, in the presence of a raised CRP." (PMID 34079538, 2021). "Both the acute HIV-1- and SARS-CoV-2-infected patients showed signs of inflammation, namely elevated C reactive protein (CRP) and ferritin levels, as expected in an acute viral infection, though IL-6 was only elevated in SARS-CoV-2-infected patients." (PMID 34578386, 2021). "Fever and elevated CRP levels strongly suggest an infection that is affecting several organ systems, such as bacterial sepsis or a systemic viral infection." (PMID 34402989, 2021). "Combined with our results, there is a clear need to examine further the importance of CRP in identifying viral infections and guiding antibiotic use, in part because it is readily available and cheaper than PCT." (PMID 34583675, 2021).
viral infections (continued). "During viral infection, white blood cells fight against the offending agent by producing cytokines that stimulate the liver to produce C-reactive protein." (PMID 34033655, 2021). "Viral infections are characterized by increased levels of interferon alpha, a cytokine shown to inhibit CRP synthesis." (PMID 34408755, 2021). "CRP can also be increased in viral infections which limits its ability to distinguish between bacterial and viral meningitis." (PMID 34115780, 2021). "CRPv and CRP2 are useful biomarkers that can discriminate significantly between patients who present with acute bacterial and viral infections, and relatively low CRP concentration upon admission who were suspected of having a bacterial infection." (PMID 34863104, 2021). "Elevated levels of C-reactive protein and procalcitonin are normally detected in patients with bacterial infections compared to those with viral infections alone." (PMID 33419872, 2021). "With increased interest in PCT research, many studies have shown that CRP is inferior to PCT in identifying bacterial or viral infections." (PMID 34583675, 2021). "Participants assigned as having definite viral infection were younger, had fewer comorbidities, and had lower leukocyte, neutrophil, and CRP counts than those with definite bacterial infections." (PMID 34423323, 2021). "Many bacterial diseases are characterized by elevated levels of circulating IL-1β and IL-6 with a concomitant increase in plasma CRP, while viral infections are commonly characterized by elevated levels of the pro-inflammatory cytokine IL-18." (PMID 35062248, 2021). "By area under the curve (AUC) analysis, we noticed that both D-Dimer (AUC 0.741) and C-reactive protein (AUC 0.707) exhibit adequate performance in predicting a poor prognosis in patients with severe viral infection." (PMID 35011795, 2021). "Although APRs are usually triggered during both bacterial and viral infections, increases of serum CRP levels in mammals are more characteristic of bacterial rather than viral infections." (PMID 33498981, 2021). "In the course of viral infections, usually normal or slightly elevated CRP concentrations are observed." (PMID 33924694, 2021). "For example, soluble TNF-related apoptosis-inducing ligand (TRAIL), IFN-γ-induced protein-10 (IP-10, CXCL10) and CRP were used in combination to distinguish between bacterial and viral infection in children and adults." (PMID 34079538, 2021). "Comparison of biomarker serum levels in bacterial vs. viral etiologies revealed that CRP levels are higher in UTI vs. viral infection whereas the levels of IP-10 and TRAIL are higher in viral infections." (PMID 34966702, 2021). "In viral infections, however, the considerable overlap with bacterial infections, indicated that CRP is less useful in this distinction." (PMID 32144345, 2020). "A significant increase in CRP levels, as documented for bacterial infections, can also occur with viral infections." (PMID 33094522, 2020). "Serum ferritin levels are particularly elevated in various viral infections, partly to extreme ranges of more than 1000 μg/L, while CRP and IL-6 values are often only mildly elevated." (PMID 32707842, 2020). "CRP is known as a common laboratory marker of systemic inflammation, and generally CRP levels are lower in viral infections than in bacterial infections." (PMID 33187475, 2020). "The combined detection of IL-6, PCT, and CRP can provide a differential diagnosis of early bacterial and viral infections." (PMID 32851063, 2020). "The distribution of leucocyte counts and CRP measurements were statistically higher in patients with bacterial infections compared to those with viral infections." (PMID 32690014, 2020). "Children and adults with bacterial infections were more often hospitalised (p values respectively < 0.0001 and 0.009) and had higher CRP values (p value 0.001 and < 0.0001 respectively) compared with patients with a viral infection." (PMID 30707378, 2019).
viral infections (continued). "For instance, in cases of chronic inflammation and viral infection, CRP levels can range from 10 to 40 mg/L." (PMID 31101112, 2019). "C-reactive protein (CRP) solution for bacterial or viral infection identification was selected as the reagent to extract the characteristic values." (PMID 31905939, 2019). "We also found that CRP was better than procalcitonin in differentiating bacterial from viral infections." (PMID 29852003, 2018). "A retrospective study based on well-characterised samples of adults and children with febrile illnesses from Cambodia, Laos and Thailand demonstrated CRP was highly sensitive and moderately specific for discriminating between bacterial and viral infections." (PMID 29852003, 2018). "Low CRP and white blood count were significant predictors of a viral infection (mainly dengue) while the presence of an eschar and elevated aspartate aminotransferase and alkaline phosphatase were important predictors of scrub typhus." (PMID 29852003, 2018). "In Southeast Asia, it has been demonstrated that CRP can discriminate between bacterial and viral infections in acutely febrile patients and reduce antibiotic use in patients with non-severe respiratory tract infections in the community." (PMID 29852003, 2018). "Only low CRP (aOR 0.972, 95%CI 0.957–0.987, p = 0.000) and low white blood count (aOR 0.573, 95%CI 0.331–0.992, p = 0.047) remained as significant predictors for viral infection on multivariate logistic regression analysis." (PMID 29852003, 2018). "A host-protein signature comprising tumor necrosis factor-related apoptosis-inducing ligand (TRAIL), interferon gamma-induced protein-10 (IP-10), and C-reactive protein (CRP) was validated recently for differentiating bacterial from viral disease." (PMID 29700762, 2018). "Eschar, white blood count and CRP were beneficial in differentiating between bacterial and viral infections in this study." (PMID 29852003, 2018). "By combining CRP and MxA into a single test, FebriDx includes sensitive markers of both bacterial and viral infection." (PMID 28991170, 2017). "This combination includes one inflammatory marker predictive for bacterial infections (CRP) and two proteins that have been shown to be upregulated in viral infections (TRAIL and IP-10)." (PMID 28753985, 2017). "CRP > 80 mg/L was measured in 52% of children with bacterial disease and in 28% of children with viral disease (p = 0.001)." (PMID 28218726, 2017). "C-Reactive Protein (CRP) has been shown to be an accurate biomarker for discriminating bacterial from viral infections in febrile patients in Southeast Asia." (PMID 26846919, 2016). "This intervention used online training modules on communication skills and on the use of C-reactive protein (CRP) to distinguish bacterial from presumed viral infections." (PMID 27267983, 2016). "The CRP test outperformed the pathogen-specific tests, with reductions in both unnecessary use of antibiotics in viral infections as well as less bacterial infections going untreated." (PMID 27027303, 2016). "It has been shown that circulating concentrations of both IL-6 and CRP are markedly higher in patients with community-acquired bacterial infections as compared to patients with viral infections." (PMID 27977798, 2016). "Biomarker testing can also reduce the unnecessary use of antibiotics in viral infection, although for CRP considerable over-treatment is likely to remain a limitation due to frequent elevation in non-bacterial infections." (PMID 27027303, 2016). "The cut-off values with the highest combined sensitivity and specificity for the identification of bacterial and viral infections using CRP were ≥7.98 mg/L and ≤7.5 mg/L, respectively." (PMID 27846213, 2016). "C-Reactive Protein and Procalcitonin levels at admittance in bacterial coinfection vs isolated virus infection." (PMID 27832114, 2016).
viral infections (continued). "CRP also remained the best predictor in the case of probable viral infection, although with marginal differences compared with the other studied parameters." (PMID 27439403, 2016). "Both PCT and CRP levels were higher in the case of bacterial involvement than in isolated viral infection, and severe cases also showed increased levels." (PMID 27832114, 2016). "When including only bacteraemias and viral infections CRP had an AUROC of 0.89 (0.8–0.97) as compared with 0.78 for procalcitonin (0.65–0.90) in distinguishing between the two aetiological groups." (PMID 26558692, 2015). "While both biomarkers were elevated in malaria and bacterial infections as compared with viral infections, CRP was the more accurate biomarker for predicting the presence of bacterial infections in these samples." (PMID 26558692, 2015). "The AUROC for CRP [0.83 (0.81–0.86)] in discriminating between all bacterial and viral infections was significantly higher than that for procalcitonin [0.74 (0.71–0.77)] (p < 0.0001)." (PMID 26558692, 2015). "The AUROC for CRP in discriminating between bacterial and viral infections was 0.83 (0.81–0.86) compared with 0.74 (0.71–0.77) for procalcitonin (p < 0.0001)." (PMID 26558692, 2015). "The near-patient CRP was introduced in primary care to differentiate bacterial from viral infections." (PMID 26141740, 2015). "Meanwhile, the slight changes observed in IL-6 and CRP levels exclude bacterial infection, thereby indicating a high probability of viral infection." (PMID 25996387, 2015). "Procalcitonin and CRP levels were significantly higher in malaria infections as compared with viral infections (p < 0.001)." (PMID 26558692, 2015). "Clinically, CRP often used to help distinguish viral infections from bacterial infections or to monitor the response to therapy." (PMID 26247033, 2015). "Viral infection is commonly assumed to increase CRP concentrations from 10 to 40 mg/L, whereas elevated CRP > 40 mg/L is mainly found in acute bacterial infections." (PMID 26247033, 2015). "Variant lymphocyte and lymphocyte levels were found highly specific and statistically superior to CRP in viral infections." (PMID 24764729, 2014). "We also found that the bacterial infections had higher mean CRP levels compared with the viral infections in POS." (PMID 24764729, 2014). "In this study, we found most patients had much higher concentrations of CRP and fibrinogen at exacerbation, probably triggered by bacterial and/or viral infections." (PMID 24618290, 2014). "PCT is upregulated through stimulation by cytokines released in response to bacterial infection, and, in contrast to CRP, is inhibited through interferon γ, which is released in viral infections, thus exhibiting a strong specificity for bacterial infections." (PMID 24612487, 2014). "The lowest median CRP concentrations were observed in viral infections (Dengue = 8.2 mg/l and Influenza = 9.6 mg/l) being significantly different to CRP levels in patients with malaria (37.9 mg/l p<0.01) and scrub typhus (26.4 p<0.006)." (PMID 24755844, 2014). "CRP differentiated bacterial infections better from viral infections than sTLR2 and sTLR4: AUC 0.94 (95% CI 0.90-0.96) versus 0.58 (95% CI 0.51-0.64) and 0.75 (95% CI 0.70-0.80), respectively [P < 0.0001 for both]." (PMID 25406630, 2014). "CRP levels showed good value to discriminate between bacterial and viral infections with an AUC of 0.94 (95% CI 0.90-0.96)." (PMID 25406630, 2014). "The cut-off values for the discrimination of bacterial infections from viral infections with a specificity of 95% were for CRP 67 mg/l (sensitivity 82%), for sTLR2 79 ng/ml (sensitivity 23%) and for sTLR4 10.6 ng/ml (sensitivity 28%)." (PMID 25406630, 2014). "Initial CRP value was considerably higher in children with bacterial infections, leading to a greater difference (ΔCRP) in this group compared to the viral infection group." (PMID 23618075, 2013).